CCDC93 (CCC complex scaffolding subunit CCDC93)
Description:
Component of the commander complex that is essential for endosomal recycling of transmembrane cargos; the commander complex is composed of composed of the CCC subcomplex and the retriever subcomplex. Component of the CCC complex, which is involved in the regulation of endosomal recycling of surface proteins, including integrins, signaling receptor and channels. The CCC complex associates with SNX17, retriever and WASH complexes to prevent lysosomal degradation and promote cell surface recycling of numerous cargos such as integrins ITGA5:ITGB1. Involved in copper-dependent ATP7A trafficking between the trans-Golgi network and vesicles in the cell periphery; the function is proposed to depend on its association within the CCC complex and cooperation with the WASH complex on early endosomes and is dependent on its interaction with WASHC2C. (Microbial infection) The CCC complex, in collaboration with the heterotrimeric retriever complex, mediates the exit of human papillomavirus to the cell surface.
Synonyms: FLJ10996
Tractability: Antibody: the Human Protein Atlas places it where antibodies can reach. PROTAC: ubiquitination databases record sites on it; its protein half-life has been measured.
Gene: Protein-coding gene on chromosome 2 (117,915,478 to 118,014,192, reverse strand). Ensembl gene ENSG00000125633.
Subcellular location: Early endosome
Subcellular location (Human Protein Atlas): Vesicles; Plasma membrane
Gene Ontology:
Molecular function: protein binding
Biological process: endocytic recycling; Golgi to plasma membrane transport
Cellular component: plasma membrane; protein-containing complex; endoplasmic reticulum membrane; endosome membrane; early endosome
Genetic constraint (gnomAD): Loss-of-function variants: 18 observed, 27.08 expected, observed/expected ratio (o/e) 0.66, 90% interval 0.46 to 0.99. The upper end of that interval is the gene's LOEUF score, 0.99, which puts it in group 4 of 6, group 1 being the genes least tolerant of losing a copy. Missense variants: 243 observed, 258.95 expected, observed/expected ratio (o/e) 0.94, 90% interval 0.84 to 1.04. Synonymous variants: 88 observed, 90.26 expected, observed/expected ratio (o/e) 0.97, 90% interval 0.82 to 1.16.
Homologues: Orthologues: chimpanzee CCDC93 (99% identical), macaque CCDC93 (98% identical), rabbit CCDC93 (95% identical), guinea pig CCDC93 (94% identical), pig CCDC93 (93% identical), rat Ccdc93 (93% identical), mouse Ccdc93 (92% identical), dog CCDC93 (91% identical), zebrafish ccdc93 (69% identical), tropical clawed frog ccdc93 (65% identical), Drosophila melanogaster fidipidine (37% identical), Caenorhabditis elegans C16A11.2 (20% identical), and 2 more.
Diseases named in the same sentence as CCDC93 in open-access papers:
CCDC93 is named in the same sentence as 8 diseases in open-access papers, as found by Europe PMC text mining. Sharing a sentence is not in itself a finding about the gene and the disease. The quoted sentences say what the papers report.
endothelial dysfunction (1 paper, 2024). In vascular diseases, endothelial dysfunction is a systemic pathological state of the endothelium (the inner lining of blood vessels) and can be broadly defined as an imbalance between vasodilating and vasoconstricting substances produced by (or acting on) the endothelium. "Ccdc93 expression was enriched in the vascular endothelium, and Ccdc93+/- mice demonstrated endothelial dysfunction, evidenced by impaired acetylcholine mediated relaxation, as well as enhanced arterial contractility." (PMID 39250516, 2024). "Based upon the findings of endothelial dysfunction in Ccdc93+/- mice, we hypothesized that vascular Ccdc93 expression is enriched in the endothelium." (PMID 39250516, 2024).
myocardial infarction (1 paper, 2024). Gross necrosis of the myocardium, as a result of interruption of the blood supply to the area, as in coronary thrombosis. "In a previous genetic study of individuals of European ancestry, CCDC93 (rs17512204; C>T, p.Pro228Leu) was associated with lower LDL-C levels, lower cardiovascular mortality, and lower risk of myocardial infarction." (PMID 39250516, 2024).
venous thromboembolism (1 paper, 2024). Occlusion of the lumen of a vein by a thrombus that has migrated from a distal site via the blood stream. "Additional CCDC93 variants have been associated with venous thromboembolism, triglyceride levels, and total cholesterol levels." (PMID 39250516, 2024).
breast (1 paper, 2014). "Mutations in gene Ccdc93 are associated with several cancers in humans, with similar observations are for Galnt6, which is probably involved in breast cancerogenesis through O-glycan processing (GO:0016266)." (PMID 25079915, 2014).
infection (1 paper, 2022). The state of being infected such as from the introduction of a foreign agent such as serum, vaccine, antigenic substance or organism. "Many of the hits were associated with intracellular transport or endosome activity, including VPS29, the CCDC22/CCDC93/COMMD3 (CCC) complex, and the WDR81/91 complex, suggesting a requirement for these functions in HCoV-OC43 infection." (PMID 35229640, 2022).
CCDC93 also shares sentences with these, for which no sentence is quoted: atherosclerosis (1 paper); cancer (1); Hypertension (1).